BRAF (B-Raf proto-oncogene, serine/threonine kinase)
Diseases named in the same sentence as BRAF in open-access papers (continued):
Sharing a sentence is not in itself a finding about the gene and the disease.
melanoma (continued). "Despite recent advances in understanding Ras signaling biology and the revolution in therapies for melanoma using BRAF inhibitors, no targeted agents have been effective in KRAS‐mutant cancers, mainly due to activation of compensatory pathways." (PMID 28173629, 2017). "An RNAi screen, targeting more than 16,500 genes in a BRAF inhibitor-sensitive melanoma cell line, identified NF1 as the highest ranking protein affected by BRAF inhibition, and that, NF1 knockdown abrogated the growth inhibitory effects of BRAF inhibition." (PMID 28637487, 2017). "Using immunohistochemistry analysis of melanoma biopsies, an improved response to BRAF and/or MEK inhibitor therapy was found in patients with no detectable stromal HGF expression, as compared with those expressing HGF." (PMID 28147313, 2017). "Furthermore, dual BRAF/MEK inhibition (dabrafenib and trametinib) was successfully employed as neoadjuvant treatment for advanced ‘in transit’ melanoma." (PMID 29100459, 2017). "Although CD271 expression may facilitate melanoma cell migration, CD271 knock-down cells (BRAF wild type) retained a residual migratory capacity, suggesting that additional, CD271-independent factors determine melanoma cell migration." (PMID 28852061, 2017). "In the current landscape, superior response rates observed with BRAF/MEK inhibitors and PD-1/CTLA-4 inhibitors have resulted in these agents supplanting HD IL-2 in the treatment of melanoma patients; particularly when coupled with the attendant complexities of HD IL-2 administration." (PMID 28923120, 2017). "Interestingly, RMEL3 was significantly higher in BRAFmt melanoma compared to triplewt (RAS/BRAF/NF1) melanoma and expression levels were negatively correlated with melanoma progression." (PMID 28350340, 2017). "Notably miR-340 is able to affect the expression of 39 out of 45 total RAS-RAF-MAPK components, such as BRAF, KRAS, NRAS and MYC, thus reducing melanoma cell growth and migration." (PMID 28118616, 2017). "Indeed, ERK inhibition was able to overcome resistance to vertical inhibition of MAPK pathway components in BRAF mutant CRC and melanoma." (PMID 28431544, 2017). "Lastly, melanoma cells were treated with benzbromarone with or without the BRAF inhibitor vemurafenib." (PMID 29285235, 2017). "The MAPK pathway is activated mainly through oncogenic mutations of BRAF or NRAS, which are early events in melanoma development and in absence of other alterations lead to oncogene induced senescence." (PMID 27449293, 2016). "Such a relationship was not previously investigated in melanoma, where the characterization of resistance mechanisms to BRAF and/or MEK inhibitors remains a major issue." (PMID 27596438, 2016). "We treated three additional BRAFV600E-positive melanoma cell lines with vemurafenib and found that each and every persistent cell population displayed consistent upregulation of JUN and phospho-JUN upon short-term BRAF inhibitor exposure." (PMID 27648299, 2016). "Although the availability of three FDA-approved MAPK pathway (BRAF and MEK) inhibitors has benefited many patients with BRAF-V600E metastatic melanoma, nearly 30% of BRAF-V600E melanomas do not respond to inhibitors of the MAPK pathway." (PMID 27655717, 2016). "The combination of ixazomib and IFN-α also enhanced inhibition of cell proliferation in BRAF V600E mutant melanoma tumor cells; however, this was not seen in BRAF wild-type cells." (PMID 27783987, 2016). "Analysis of responsiveness to BRAF, MEK1/2 and PI3K/mTOR inhibitors in a few short term melanoma cell cultures, from patients subsequently treated with target therapy, suggested that drug susceptibility data may predict response or resistance to treatment." (PMID 26678033, 2016). "In addition, we used BRAF specific siRNAs, PLX-4032 and several inhibitors of the MAPK pathway to investigate the role of this pathway in the regulation of CD70 expressed by melanoma cells." (PMID 26828592, 2016).
melanoma (continued). "However, the correlation between Rho GTPases, BRAF and MAPK pathway activation status and CD70 expression in CD70+ melanoma cells is yet to be described." (PMID 26828592, 2016). "We found that sabutoclax treatment was very effective not only in BRAFV600E-expressing lines, regardless of PTEN status, but also in non-BRAF melanomas that currently have no effective clinical options." (PMID 27846237, 2016). "We found that the BRAF mutant or BRAF wild type patients in melanoma group, and the squamous cancer patient or non-squamous cancer patients in NSCLC group had gained better outcome of survival." (PMID 27542277, 2016). "In addition, we have identified a set of SCNAs, including amplification of BRAF and EZH2, in thick melanomas that subsequently developed metastasis." (PMID 27095580, 2016). "Nelfinavir profoundly sensitizes BRAF and NRAS mutant melanoma cells to MAPK-pathway inhibitors." (PMID 26977879, 2016). "Furthermore, CTHRC1 was recognized as an important mediator of melanoma cell migration and invasion, providing together with its regulators—NFATC2, TGFβ, and BRAF—attractive therapeutic targets against metastatic melanomas." (PMID 26918341, 2016). "Several observations focused attention on the immunomodulatory effect of BRAF/MEK inhibitors, that induce an increase of melanoma antigens expression and of CD8+ lymphocyte intratumoral infiltration, and a reduction of the release of several immunosuppresive cytokines." (PMID 26981153, 2016). "Since we did not detect any NRG1-beta in the BRAF wild-type cell line MeWo, we investigated two other BRAF wild-type cell lines, the metastatic melanoma cell line WM1382 and the immortalized melanocyte cell line Hermes 4C." (PMID 27391157, 2016). "Optimal sequencing of available treatment options for patients with BRAF V600 mutant melanoma has not been defined." (PMID 27095081, 2016). "While the activation of the PI3K pathway and loss of PTEN have been previously linked to resistance to BRAF or MEK inhibitors, we found that neither were sufficient to render BRAF-V600E melanoma cells resistant to SCH984." (PMID 27655717, 2016). "Moreover, nelfinavir is effective in BRAF and NRAS mutant melanoma cells isolated from patients progressed on MAPK inhibitor (MAPKi) therapy and in BRAF/NRAS/PTEN mutant tumors." (PMID 26977879, 2016). "Both BRAF and NRAS mutations are known to deregulate the MAPK pathway, functioning as mutually exclusive aberrations in melanoma not exposed to BRAF-inhibitors." (PMID 27447557, 2016). "discover PAX3-mediated overexpression of MITF as a reversible resistance mechanism to MAPK-pathway inhibition in BRAF mutant melanomas and identify nelfinavir, which inhibits this mechanism and sensitizes not only BRAF mutant but also BRAF and NRAS mutant melanoma cells to MAPK-pathway inhibitors." (PMID 26977879, 2016). "To investigate the role of SOX10, MITF, and FOXD3 and the reported effects due to BRAF status in ERBB3 regulation, we depleted the three former genes individually and in combination for MITF/FOXD3 by the use of siRNA in three melanoma cell lines: WM983B, MeWo and WM115." (PMID 27391157, 2016). "A MCL-1 specific inhibitor sabutoclax treatment is very effective not only in BRAFV600E-expressing lines, but also in non-BRAF melanomas that currently have no effective clinical options in the clinic." (PMID 27846237, 2016). "Among 49 BRAF-mutant melanoma cell lines from patients not previously treated with target therapy, 21 (42.9%) showed strong primary resistance (IC50 > 1 μM) to a BRAFV600E inhibitor." (PMID 26678033, 2016). "To investigate a link between MAPK pathway activation and TERT expression in presence or absence of TERT promoter mutation, we performed experiments on nine melanoma cell lines with or without TERT, BRAF and NRAS mutations." (PMID 27449293, 2016).
melanoma (continued). "Combining a selective BRAF inhibitor, such as dabrafenib, and a MEK inhibitor, such as trametinib, has been shown to improve the response rate and progression-free survival in patients with advanced melanoma." (PMID 27461275, 2016). "Interestingly, inhibition of ROCK (using Y27632), a downstream target of RHOA signalling, also induces CDKN1A in melanoma, and ROCK1 has been identified as a potential candidate for combinatorial therapy with BRAF inhibitors." (PMID 27835901, 2016). "Furthermore, activated PI3K signaling overcomes BRAF mediated senescence and potentiates environmental escape by inducing EMT in melanoma cells." (PMID 26517521, 2016). "We found a strong inverse correlation between the mRNA expression of ZEB1 and MITF in melanoma cell lines from the Cancer Cell Line Encyclopedia (CCLE), regardless of their BRAF/NRAS mutational status (n = 61, P = 4.08E‐11)." (PMID 27596438, 2016). "Western blots showed 100μM propranolol significantly reduced the expression of Bcl-2 while increasing the expressions of Bax, cytochrome c, cleaved capase-9 and cleaved caspase-3, and down-regulated the levels of p-AKT, p-BRAF, p-MEK1/2 and p-ERK1/2 in melanoma cells, after a 24h incubation." (PMID 27582542, 2016). "In addition, we have identified a set of SCNAs, including amplification of BRAF and ofthe epigenetic modifier EZH2, that are specific for the group of thick melanomas that developed metastasis during the follow-up." (PMID 27095580, 2016). "Another small molecule SBI-0640756 (SBI-756), a first-in-class inhibitor that targets EIF4G1 and disrupts the EIF4F complex, can effectively inhibit the growth of NRAS, BRAF, and NF1-mutant melanomas in vitro and delay the onset and reduce the incidence of Nras/Ink4a melanomas in vivo." (PMID 27003362, 2016). "In the second phase III trial, nivolumab was compared with chemotherapy in patients with advanced melanoma non-responsive to ipilimumab (or ipililumab and BRAF inhibitor in BRAF-mutant tumors)." (PMID 28018338, 2016). "Indeed, primary cross-resistance to BRAF and MEK inhibitors has been documented in a subset of melanomas, where it is related to the MITF profile, and in cell lines." (PMID 26678033, 2016). "Clinically, vemurafenib is not currently used for the treatment of non-BRAF mutant melanoma due to a lack of efficacy and the paradoxical transactivation of the key driver of melanomagenesis, the MAPK pathway, and the subsequent cell proliferation." (PMID 27447557, 2016). "Under this respect, it is noteworthy that OP-A is effective at nanomolar/micromolar concentrations after 24 h of treatment, whereas the BRAF inhibitor vemurafenib, the elective drug for treatment of recalcitrant melanomas is not (data not shown)." (PMID 27936075, 2016). "Meanwhile, there are no effective treatment options available for wildtype-BRAF/NRAS melanomas, which constitute ~30% of all melanomas." (PMID 27846237, 2016). "On the other hand, mutant BRAF (V600E) has been reported to constitutively phosphorylate ERK which can phosphorylate LKB1 directly or indirectly through ribosomal S6 kinase (RSK), and subsequently suppress LKB1 capability to activate AMPK in melanomas." (PMID 26771234, 2016). "They used these models to perform a large-scale 1×1×1 (1 mouse representing 1 patient tumor in1 treatment group) trial to retrospectively verify the results of clinical trials testing BRAF inhibitors and the BRAF/MEK inhibitor combination in BRAF mutant melanoma." (PMID 27608848, 2016). "Melanomas with no detectable BRAF or NRAS mutations were more common in head and neck melanomas (19.8%) compared to either BRAF (10.0%) or NRAS (8.9%) mutant melanomas." (PMID 27191502, 2016). "Lito and colleagues recently demonstrated that MEK activated by CRAF in melanoma and lung cancer cells is less sensitive to MEK inhibitors than when activated by BRAF V600E, which is confirmed by the response of KTC1-VEM2 cells to combination treatment with vemurafenib and the MEK inhibitor AZD6244." (PMID 27127178, 2016).
melanoma (continued). "Conversely, oncogenic BRAF induces a chronic ER stress status, resulting in enhanced basal autophagy [as evidenced by increased Atg8-PE/LC3-II (LC3-II) expression], resistance of melanoma cells to apoptosis, and insensitivity to further autophagy induction." (PMID 27882308, 2016). "Activating somatic mutations of BRAF, most commonly via substitution of valine for glutamic acid at codon 600 (BRAF V600E), have been shown to result in constitutive activation of the MAPK pathway in several human cancers, including malignant melanomas and thyroid tumors." (PMID 29056712, 2016). "Similarly, KIT mutant human melanoma lines were able to populate a larger area in a 3D in vitro skin model compared to KIT wild type and BRAF mutant lines." (PMID 27322141, 2016). "In BRAF-mutant melanoma, targeting the MAPK pathway alone is not sufficient to induce apoptosis in the entire tumour population." (PMID 26857260, 2016). "In addition to the development of BRAF and MEK inhibitors, breakthroughs in the field of immunotherapy have also dramatically impacted the treatment landscape for advanced melanoma." (PMID 26784231, 2016). "This is supported by Abel and Aplin, who showed that FOXD3 does not regulate ERBB3 expression in BRAF wild-type melanoma cells, nor in melanocytes." (PMID 27391157, 2016). "Major limitations of current melanoma treatments are for instances of relapse and the lack of therapeutic options for BRAF wild-type patients who do not respond to immunotherapy." (PMID 27829238, 2016). "Recent data implicate elevated transforming growth factor-β (TGFβ) signalling in BRAF inhibitor drug-resistance mechanisms, but the potential for targeting TGFβ signalling in cases of advanced melanoma has not been investigated." (PMID 27835901, 2016). "LncRNA RMEL3 in necessary for the activation of BRAF and AKT in melanoma cell lines." (PMID 27340923, 2016). "Concurrent targeting BRAF and MEK has been considered the possibility to enhance tumor growth inhibition, delay acquired resistance, and abrogate paradoxical activation of the MAPK pathway in preclinical models of melanoma." (PMID 26143635, 2015). "Our analysis of the exome re-sequencing data from the same TCGA cohort did not identify specific enrichments for mutations in BRAF, NRAS or any of the other well-established melanoma driver genes (n=116) in either of the clusters." (PMID 25865119, 2015). "Further studies are needed to define the relationship between EZH2 and MAP kinase signaling but these results suggest that combining BRAF and EZH2 inhibitors may provide an effective treatment strategy for melanoma." (PMID 26304929, 2015). "This allows BRAF to assume control over the regulation of MITF expression, and BRN2 depletion abolishes the ability of BRAFV600E to activate the MITF promoter in human melanoma cells." (PMID 25818589, 2015). "Thus, BRAF and NRAS mutant melanomas contain a subpopulation of cells intrinsically resistant to MEK inhibitors, which displays a classic OXPHOS phenotype and PGC1α-dependent mitochondrial biogenesis." (PMID 26713093, 2015). "It is not clear what upregulates AXL or WNT5A expression, but BRAF inhibition in a panel of BRAFmut/AXL+ melanoma cells does not reduce AXL expression." (PMID 25818589, 2015). "Our data suggest that loss of RIPK3 in melanoma and selective inhibition of the RIPK3/MLKL axis by BRAF inhibitor Dabrafenib, but not Vemurafenib, is critical to protect from necroptosis." (PMID 26355347, 2015). "Cell lines with low RHOB expression were more sensitive to PLX4032, suggesting that, in melanoma cells, high RHOB expression may predict a poor response of BRAF-mutant patients to PLX4032." (PMID 26098773, 2015). "However, in the case of NRAS mutant melanomas, due to the paradoxical activation of the MAPK pathway, specific BRAF inhibitors cannot be used." (PMID 25645078, 2015).
melanoma (continued). "In addition, combination therapy of BRAF inhibitors with allosteric MEK1 and MEK2 inhibitors are also in clinical trials and have been approved for treatment for BRAF mutant melanomas." (PMID 26139106, 2015). "In Melanoma, knockdown of BRAFV600E was shown to profoundly reduce the expression levels of EZH2, suggesting that increased BRAF activity frequently found in melanoma may contribute to the abnormal overexpression of EZH2." (PMID 26304929, 2015). "In the phase II expansion study, 162 advanced melanoma patients with BRAFV600 mutation and no prior BRAF targeted therapy were assigned 1:1:1 to receive dabrafenib (150 mg QD) and trametinib (either 1 or 2 mg QD) or dabrafenib (150 mg QD) monotherapy." (PMID 27508107, 2015). "Similarly, BRAF inhibition induces phosphorylation of PERK and is crucial for autophagosome formation in melanoma." (PMID 26622781, 2015). "BAY 87-2243 induced a significant reduction in tumor size in all BRAF mutant melanoma xenografts, as well as a reduction in tumor weight without affecting body weight of the mice." (PMID 26500770, 2015). "The primary endpoint of the study was PFS in patients with BRAF V600E-mutant melanoma with no prior brain metastases." (PMID 26171394, 2015). "While targeted therapy brought a new era in the treatment of BRAF mutant melanoma, therapeutic options for non-BRAF mutant cases are still limited." (PMID 25646931, 2015). "For instance, vemurafenib was effective in BRAF V600E mutant melanoma but had no activity in BRAF V600E mutant colon cancer." (PMID 26474971, 2015). "We demonstrate that BAY 87-2243-mediated complex I inhibition induced significant reduction of cell viability in a dose-dependent manner in several BRAFV600E (G-361, SK-MEL-5, SK-MEL-28, and A-375) and also BRAF wild type (SK-MEL-2, IPC-298, CHL-1, and Colo-792) melanoma cell lines." (PMID 26500770, 2015). "IGF-1Ri sensitized BRAF wild-type and mutant melanoma cells to TMZ in vitro, an effect that was independent of MGMT." (PMID 26497996, 2015). "Without treatment with selective BRAF inhibitors, patients with BRAF V600E-mutant melanoma generally have a poorer prognosis than those with wild-type BRAF." (PMID 25962795, 2015). "Another study suggests, however, that intrinsically resistant melanomas can be characterized by low expression/activity of MITF accompanied by enhanced activity of NF-κB signaling, and BRAF inhibition in MITF-high, drug-sensitive cells induces a transition to the MITF-low/NF-κB–high state." (PMID 25433395, 2015). "We first tested melanoma cells in culture, characterizing A375P (homozygous BRAFV600E), Mel624 (heterozygous BRAFV600E), and MeWo (homozygous BRAF WT) cell lines for BRAF protein expression (Pan-RAF and mutant BRAFV600E) on western blotting and immunofluorescence." (PMID 25807549, 2015). "In summary, we have found an effective combination to treat malignant melanomas which do not express ASS, regardless of their BRAF mutation status." (PMID 25749046, 2015). "Gene fusions involving RAF kinase genes (BRAF, RAF1, CRAF) have been identified in low-grade tumors of the central nervous system (pilocytic astrocytomas and other low-grade gliomas), gastric cancer, melanoma and prostate cancer." (PMID 26684754, 2015). "As expected, melanoma patients with advanced disease showed varying levels of BRAF V600E, while patients with lower stages of melanoma were negative." (PMID 26562020, 2015). "For these reasons, the oncogenic RAF-MAPK axis is nowadays used as a target for cancer therapies and specific BRAF and MEK inhibitors have been now approved by FDA (US Food and Drug Administration) for the treatment of diseases such as melanoma and lung cancer." (PMID 26513174, 2015). "Vincristine is rarely used in melanoma therapeutic regimens and EGFR family members are not known to have a driver role in melanomas except in adaptive resistance to BRAF inhibitors." (PMID 26461489, 2015).